TPX2 (TPX2 microtubule nucleation factor)
Diseases named in the same sentence as TPX2 in open-access papers (continued):
Sharing a sentence is not in itself a finding about the gene and the disease.
pancreatic cancer (continued). "The upregulation of IGFBP-3 induced by TPX2 silencing may be at least partly responsible for the inhibitory effect on proliferation and angiogenesis in pancreatic cancer cells." (PMID 25914189, 2015). "TPX2 expression was also confirmed in several pancreatic cancer cell lines." (PMID 25914189, 2015). "However, this experimental protocol only tested the mechanistic role of TPX2 in pancreatic cancer cell growth because the investigators implanted TPX2 siRNA-treated cancer cells." (PMID 25914189, 2015). "Moreover, the direct injection of TPX2 siRNA into the subcutaneously implanted pancreatic cancer cells in nude mice revealed an antiproliferative effect." (PMID 25914189, 2015). "The results also implied that the antiangiogenic effect observed in TPX2 siRNA-treated pancreatic cancer cells may be partly explained by the upregulation of IGFBP-3." (PMID 25914189, 2015). "Therefore, in the subsequent animal studies using KLM1, we selected TPX2 siRNA-2 as a treatment agent for pancreatic cancer." (PMID 25914189, 2015). "The level of TPX2 was correlated with the progression of pancreatic cancer." (PMID 25914189, 2015). "In addition, specific targeting of TPX2 with short interfering RNAs in pancreas cancer cells results in decreased proliferation and tumorigenicity." (PMID 23785665, 2013). "Therefore, we compared tumors treated with TPX2 siRNA and Control siRNA using a protein array containing angiogenesis factors to elucidate whether TPX2 has any effect on angiogenesis in pancreatic cancer." (PMID 25914189, 2015). "TPX2 is a well-established oncogene with high expression level in varieties of tumors, including HCC, pancreatic cancer, and esophageal squamous carcinoma, the regulatory mechanism of its expression, however, is not clear yet." (PMID 32723329, 2020). "Further study is necessary to elucidate the regulatory interaction between TPX2 and IGFBP-3 in pancreatic cancer and other types of cancers." (PMID 25914189, 2015). "Although the correlation between TPX2 expression and tumor angiogenesis has not been reported before, our results indicated that TPX2 has an impact on tumor angiogenesis in pancreatic cancer." (PMID 25914189, 2015). "However, TPX2 protein was not identified in normal pancreas and PanIN (pancreatic intraepithelial neoplasia), which is precursor lesion of pancreatic cancer." (PMID 25914189, 2015).
cervical cancer (17 papers, 2014 to 2025). A primary or metastatic malignant neoplasm involving the cervix. "In cervical cancer, TPX2 is often overexpressed, causing abnormal spindle formation and unchecked cell division." (PMID 40519296, 2025). "Since both IMP3 and TPX2 have been associated with growth of cervical cancer, we speculated that they might also be associated with growth of CIN." (PMID 26624896, 2015). "Statistical association between elevated TPX2 levels and lymph node metastasis have been reported in esophageal squamous cell carcinoma squamous cell lung cancer, medullary thyroid carcinoma, cervical cancer, and bladder carcinoma." (PMID 25368990, 2014). "For instance, hsa_circRNA_101996 promotes the proliferation and invasion of cervical cancers by sponging miR-8075 and by activating TPX2 expression." (PMID 35783013, 2022). "It was found in cervical cancer that circRNA hsa_circRNA_101996 activates the expression of TPX2 by inhibiting miR-8075, thereby enhancing the proliferation and invasion of cervical cancer." (PMID 33680975, 2021). "At the same time, cell biology methods were used to verify that the upregulation of TPX2 by miR-8075, mediated by has_circRNA_101996, is helpful to the proliferation, migration, and invasion of cervical cancer." (PMID 33880120, 2021). "Studies have shown that hsa_circRNA_101996 can act as a sponge for miR-8075 and then target TPX2 in cervical cancer cells." (PMID 33880120, 2021). "It has been shown that activation of TPX2 expression increases the invasion and proliferation of cervical cancer, promoting cancer development." (PMID 33912448, 2021). "TPX2 is highly expressed at both the mRNA and protein level in many types of cancers, including lung, hepatic, colon, pancreatic, salivary gland, and cervical cancers." (PMID 28069036, 2017). "In cervical cancer, the expression of TPX2 was correlated with histological grading, FIGO staging, and lymph node metastasis." (PMID 28562334, 2017). "Overexpression of TPX2 has been reported in many types of tumors, including those from lung, hepatic, colon, pancreatic, salivary gland, and cervical cancers." (PMID 28069036, 2017). "Targeting protein for xenopus kinesin-like protein 2 (TPX2) has been demonstrated to be overexpressed in cervical cancer." (PMID 26624896, 2015). "Moreover, upregulated circRNA hsa_circRNA_101996 serves as a miR-8075 sponge to target TPX2 in cervical cancer, thereby promoting cervical cancer proliferation and invasion." (PMID 34392306, 2021). "The simulation interaction diagram analysis highlights the detailed interactions between Pixuvri and four key cervical cancer-related protein targets: BubR1 (PDB ID: 2WVI), Cell Division Cycle Protein 20 Homolog (PDB ID: 4N14), MAD2 (PDB ID: 2VFX), and TPX2 (PDB ID: 3KND)." (PMID 40519296, 2025).
lung adenocarcinoma (17 papers, 2008 to 2026). A carcinoma that arises from the lung and is characterized by the presence of malignant glandular epithelial cells. "Employing multiple datasets, elevated expression of TPX2 was implicated in multiple cancer types, including Hepatic cell cancer, lung adenocarcinoma, and non-small cell lung cancer, thus corroborating an essential function for TPX2 in multiple cancers." (PMID 37770979, 2023). "In vitro experiments in lung adenocarcinoma (LUAD) were performed to confirm the potential role of TPX2." (PMID 38315450, 2024). "Furthermore, TPX2 expression has been linked to tumor microenvironments and immune cell infiltration, particularly in bladder urothelial carcinoma, liver hepatocellular carcinoma, lung adenocarcinoma, stomach adenocarcinoma, and uterine corpus endometrial carcinoma." (PMID 36304254, 2022). "In TCGA lung adenocarcinoma data sets there was a small, statistically significant increase in HURP, AURKA, TPX2 or RAN mRNA levels correlating with SMARCA4 mutations of all types." (PMID 28102363, 2017). "Targeting protein for Xklp2 (TPX2) is a known mitotic regulator overexpressed in lung adenocarcinoma (LUAD), yet its role in cancer stemness and autophagy remains unclear." (PMID 42311261, 2026). "Additionally, qRT-PCR was conducted on 30 paired lung adenocarcinoma and squamous cell carcinoma samples of local hospital (different from the 107 samples used to make tissue array) to validate the relation between TOP2A and TPX2." (PMID 31528121, 2019).
glioma (16 papers, 2014 to 2025). A benign or malignant brain and spinal cord tumor that arises from glial cells (astrocytes, oligodendrocytes, ependymal cells). "What’s more, loss-of-functional experiment suggested that knockdown of TPX2 repressed proliferation and aerobic glycolysis, while induced apoptosis in glioma cells." (PMID 32774168, 2020). "Single-cell analysis revealed that TPX2 was mainly distributed in malignant cells (especially in glioma) and proliferating T cells." (PMID 38315450, 2024). "In gliomas, MiR-1294 can target TPX2 to inhibit tumor cell proliferation and enhance sensitivity to chemotherapy." (PMID 34917126, 2021). "recently confirmed that circPOSTN was overexpressed in glioma tissues and induced tumor cell proliferation by targeting the miR-361-5p/TPX2 axis." (PMID 34745938, 2021). "Based on above studies, we measured the abundance of circPOSTN, miR-361-5p and TPX2 in glioma tissues and cells." (PMID 32774168, 2020). "Most importantly, the current study was the first to show that the detailed role and mechanism of circPOSTN/miR-361-5p/TPX2 axis in aerobic glycolysis of glioma cells, providing a novel and potential therapy strategy for glioma." (PMID 32774168, 2020). "Accordingly, the study was committed to probing the mechanism of circPOSTN/miR-361-5p/TPX2 axis on glioma." (PMID 32774168, 2020). "To further figure out the role of TPX2 in glioma, we knocked down TPX2 in LN229 and U251 cells by introducing with si-TPX2." (PMID 32774168, 2020). "Currently, glioma tissues and cells exhibited upregulation expression of TPX2, and TPX2 was inversely correlated with miR-361-5p expression in glioma tumor tissues." (PMID 32774168, 2020). "Mechanistically, circPOSTN regulated cell growth, apoptosis, and aerobic glycolysis in glioma through miR-361-5p/TPX2 axis." (PMID 32774168, 2020). "In glioma, miR-1294 inhibited cell proliferation and contributed to chemosensitivity via directing TPX2." (PMID 30988074, 2019). "Furthermore, the circPOSTN expression increased in glioma tissues, which in turn controls the expression of TPX2 via sponge miR-361-5p, ultimately promoting the growth and aerobic glycolysis of glioma tissues." (PMID 40723354, 2025). "TPX2 expression was up-regulated in malignant cells of the glioma microenvironment." (PMID 38315450, 2024). "Single-cell analysis revealed that TPX2 expression was up-regulated within malignant glioma cells." (PMID 38315450, 2024). "Furthermore, through the miR-361–5p/TPX2 signaling pathway, highly expressed circPOSTN participated regulating TPX2 expression in glioma cells, resulting in enhanced proliferation and aerobic glycolysis." (PMID 38075205, 2024). "Moreover, inhibitors of HDAC possess the ability to reduce the expression of TPX2, mitotic spindle formation-related protein in glioma cells and in human glioblastoma multiforme primary cultures." (PMID 35395834, 2022). "Importantly, previous studies reported that AIFM3, LDHD, LYNX1, SCN2B or TMEM56 were all negatively corelated with glioma, and GINS1, KIFC1, NUF2, NUSAP1 or TPX2 were both positively related to glioma progression." (PMID 33277782, 2021). "In addition, mechanistic analysis experiments revealed that circPOSTN silencing impeded glioma cells growth, while induced apoptosis by targeting miR-361-5p/TPX2 axis." (PMID 32774168, 2020). "Moreover, the results of RT-qPCR and western blot assays implied that TPX2 was highly expressed in glioma tissues and cells with respect to matched controls." (PMID 32774168, 2020). "As previous research had reported that targeting protein for Xenopus kinesin-like protein 2 (TPX2) could promote glioma progression by activating the protein kinase B (AKT) signaling pathway." (PMID 32774168, 2020). "In addition, the diagrammatic representation of our results suggested that circPOSTN/miR-361-5p/TPX2 axis regulated cell growth, apoptosis and aerobic glycolysis in glioma cells." (PMID 32774168, 2020).
glioma (continued). "Moreover, deletion of circPOSTN or TPX2 significantly repressed cell proliferation and aerobic glycolysis, while induced apoptosis of glioma cells." (PMID 32774168, 2020). "In addition, circPOSTN targetedly regulated TPX2 expression in glioma cells via sponging miR-361-5p." (PMID 32774168, 2020). "In this study, we found that miR-361-5p could interact with TPX2 in glioma cells by dual-luciferase reporter assay." (PMID 32774168, 2020). "Furthermore, downregulation of TPX2 contributed to apoptosis and inhibited proliferation and aerobic glycolysis in glioma cells." (PMID 32774168, 2020). "Thus, it was concluded that knockdown of TPX2 impeded process of glioma by regulating proliferation, apoptosis, and aerobic glycolysis in glioma cells." (PMID 32774168, 2020). "Moreover, Pearson’s correlation analysis suggested that TPX2 was positively correlated with circPOSTN expression in glioma tissues." (PMID 32774168, 2020). "In addition, HDACi reduce the expression of proteins involved in DNA repair (Rad51), mitotic spindle formation (TPX2) and chromosome segregation (Survivin) in glioma cells and in human glioblastoma multiforme primary cultures." (PMID 25275596, 2014). "Additionally, miR-361-5p, interacted with TPX2, was a target gene circPOSTN, suggesting circPOSTN/miR-361-5p/TPX2 axis may be a new therapeutic target for the diagnosis and treatment of glioma in the future." (PMID 32774168, 2020). "In particular, in the glioma GSE131928 10× dataset, TPX2 was primarily expressed in malignant cells compared with other cells." (PMID 38315450, 2024). "A second study showed that circPOSTN or TPX2 knockdown could inhibit HK2 expression levels, indicating that circPOSTN might be involved in glioma progression by affecting aerobic glycolysis." (PMID 34745938, 2021).
bladder cancer (15 papers, 2014 to 2025). "After hnRNP-F knockdown, TPX2 levels were found to decline even further, causing cyclin D1 protein expression to decrease and p21 protein expression to increase, resulting in cell cycle arrest and the reduced proliferation of bladder cancer cells." (PMID 36304254, 2022). "However, there are many literatures that have demonstrated that TPX2 is significantly associated with bladder cancer." (PMID 36316768, 2022). "TPX2 has been associated with metastasis and the prognosis of bladder cancer." (PMID 34142021, 2021). "In bladder cancer, TPX2 is involved in TPX2-mediated phosphorylation of the AURKA-PI3K-AKT axis." (PMID 35806060, 2022). "Thus, we conclude that TPX2 plays an important role in the progression of bladder cancers, including CIS in disease course, and represents a good potential marker for targeted therapy." (PMID 35806060, 2022). "In addition, heterogeneous nuclear ribonucleoprotein F, by regulating the TPX2 protein, promotes the cell cycle and proliferation of bladder cancer cells." (PMID 35806060, 2022). "Previous studies have demonstrated that TPX2 promotes AURKA activation and downstream PI3K/AKT signaling, thereby facilitating angiogenesis in bladder cancer cells." (PMID 40564876, 2025). "In conclusion, we believe that these five target genes (GSK3B, CDC20, TPX2, AURKA and CCNE1) may promote the occurrence of bladder cancer and lead to poor prognosis.We explored the potential therapeutic targets of aspirin for bladder cancer by comprehensive bioinformatics analysis." (PMID 36316768, 2022).
colorectal cancer (15 papers, 2019 to 2025). A primary or metastatic malignant neoplasm that affects the colon or rectum. "The main diseases known to be associated with the TPX2 gene include Capillary Leak Syndrome and Colorectal Cancer." (PMID 33912448, 2021). "Other genes of the locus with potential pathogenic importance in colorectal cancers, such as TPX2, KIF3B and POFUT1, are also amplified in the 12 cell lines." (PMID 34577783, 2021). "In colorectal cancer, TPX2 is closely associated with tumor-infiltrating lymphocytes." (PMID 38833082, 2024). "Furthermore, in breast and colorectal cancers, TPX2 has been identified as a MYC-cooperating oncogene that drives tumorigenesis." (PMID 40564876, 2025). "Overexpression or knockdown of TPX2 in PXR-positive colorectal cancer cells LS180 could affect PXR activity in LS180 cells." (PMID 36707511, 2023). "Furthermore, TPX2 is overexpressed in primary colorectal cancer tissues." (PMID 36789877, 2023). "Over-expression of amplified genes is partially overlapping with the over-expression of the genes in 20q11.21 amplified clinical samples of colorectal cancer patients, where POFUT1 but also ASXL1, and, in fewer cases, KIF3B and TPX2, are often over-expressed." (PMID 34577783, 2021).
liver cancer (14 papers, 2018 to 2025). An epithelial or non-epithelial malignant neoplasm that arises from the liver. "A violin plot shows that the expression of AKR1C3, NQO1, TEK and TPX2 was significantly associated with different disease states (normal, cirrhosis or liver cancer) (p < .05) (GSE54238)." (PMID 36686655, 2022). "We found that knockouts of AKR1C3 or TPX2 can significantly inhibit the invasion of liver cancer cells." (PMID 36686655, 2022). "Understanding this interaction may provide crucial information on TPX2's role in liver cancer progression and survival." (PMID 38914609, 2024). "The data presented indicate that Anln, Hmmr, Tpx2, Ccnb1, and Ccnb2 may be influenced by changes in miR-122 expression and potentially contribute to liver cancer development." (PMID 37566034, 2023). "We further explored the impact of AKR1C3 or TPX2 on the development of liver cancer in vitro." (PMID 36686655, 2022). "And the knockouts of AKR1C3 or TPX2 can significantly inhibit the invasion of liver cancer cells." (PMID 36686655, 2022). "Finally, survival analysis, based on clinical information from the TCGA-liver cancer datasets, revealed that the high expression of EZH2, GINS1, and TPX2 correlated positively with higher risk, CENPF and BUB1B were quite the contrary." (PMID 30100882, 2018). "Notably, and in agreement with what was observed in the mouse models of liver cancer, ANLN, HMMR, TPX2, CCNB1, and CCNB2 expressions were found to be significantly upregulated in TCGA-LIHC." (PMID 37566034, 2023). "Previous clinical studies have shown that the expression of TPX2 in liver cancer tissue is significantly related to tumor-node-metastasis stage, tumor number, differentiation, and stage." (PMID 34257537, 2021). "In addition to CCNB1, CDK1, CDC45, BUB1B, and CCNA2, we also identified five hub genes in Chinese liver cancer, namely AURKA, KIF11, TOP2A, TPX2, and HMMR, which play a crucial role in regulating the cell cycle." (PMID 34257537, 2021). "Moreover, the low protein expression levels of TPX2 were revealed in normal liver tissues, while low (1/6) and medium (4/6) even none (1/6) protein expression levels were observed in liver cancer tissues." (PMID 34257537, 2021).